ALDH16A1 (aldehyde dehydrogenase 16 family member A1)
Synonyms: MGC10204
Tractability: Small molecule: it belongs to a druggable protein family. PROTAC: ubiquitination databases record sites on it; its protein half-life has been measured.
Target class: Enzyme; Oxidoreductase
Gene: Protein-coding gene on chromosome 19 (49,453,146 to 49,471,052, forward strand). Ensembl gene ENSG00000161618.
Gene Ontology:
Molecular function: protein binding; aldehyde dehydrogenase (NAD+) activity; oxidoreductase activity
Biological process: aldehyde metabolic process
Cellular component: membrane
Genetic constraint (gnomAD): Loss-of-function variants: 88 observed, 88.79 expected, observed/expected ratio (o/e) 0.99, 90% interval 0.83 to 1.18. The upper end of that interval is the gene's LOEUF score, 1.18, which puts it in group 5 of 6, group 1 being the genes least tolerant of losing a copy. Missense variants: 1,250 observed, 1,038.1 expected, observed/expected ratio (o/e) 1.2, 90% interval 1.15 to 1.26. Synonymous variants: 522 observed, 453.28 expected, observed/expected ratio (o/e) 1.15, 90% interval 1.07 to 1.24.
Homologues: Orthologues: chimpanzee ALDH16A1 (98% identical), macaque ALDH16A1 (96% identical), pig ALDH16A1 (86% identical), dog ALDH16A1 (85% identical), mouse Aldh16a1 (82% identical), guinea pig ALDH16A1 (79% identical), rat Aldh16a1 (76% identical), rabbit ALDH16A1 (73% identical), zebrafish aldh16a1 (34% identical), Caenorhabditis elegans alh-2 (16% identical), Caenorhabditis elegans alh-1 (16% identical), Drosophila melanogaster CG31075 (16% identical), and 2 more. Paralogues in human: ALDH9A1 (18% identical), ALDH1A2 (18% identical), ALDH2 (17% identical), ALDH1A1 (17% identical), ALDH1B1 (17% identical), ALDH1A3 (16% identical), ALDH1L1 (16% identical), ALDH5A1 (15% identical), ALDH1L2 (15% identical), ALDH8A1 (15% identical), ALDH4A1 (14% identical), ALDH7A1 (14% identical), and 5 more.
Diseases named in the same sentence as ALDH16A1 in open-access papers:
ALDH16A1 is named in the same sentence as 9 diseases in open-access papers, as found by Europe PMC text mining. Sharing a sentence is not in itself a finding about the gene and the disease. The quoted sentences say what the papers report.
gout (6 papers, 2014 to 2023). A condition characterized by painful swelling of the joints, which is caused by deposition of urate crystals. "Mutation in the ALDH16A1 gene can influence uric acid homeostasis and is associated with the pathogenesis of gout in humans and Mast syndrome." (PMID 36694633, 2023). "Results from a study utilizing whole-genome sequencing in a group of Icelanders revealed a rare missense single nucleotide polymorphism (SNP) in Aldh16a1 and it was associated with gout and hyperuricemia." (PMID 37686694, 2023). "Some of the previously reported gout associated loci (except ALDH16A1), including ABCG2, SLC2A9, GCKR, ALDH2 and CNIH2, were replicated." (PMID 28642574, 2017). "ALDH16A1 gene is associated with serum uric acid levels and gout, and RNA sequencing in the kidney of wild-type (WT) and Aldh16a1 knockout (KO) mice revealed changes in Slc16a9 are localized to the apical membrane of the proximal convoluted tubule cells and influence uric acid homeostasis." (PMID 32090094, 2020). "When analyzing gout as the phenotype, two loci reached genome-wide significance: a novel association with an exonic SNP in ALDH16A1 (P = 1.4 × 10−16), and a Q141K variant within ABCG2 (P = 2.82 × 10−12), a gene previously reported to be associated with gout and serum uric acid levels." (PMID 25789374, 2014). "The hypothesis that ALDH16A1 interacts with hypoxanthine-guanine phosphoribosyltransferase (HPRT1), which is implicated in the metabolism of uric acid and gout, was supported by the fact that the carriers of the variant present hyperuricemia." (PMID 37686694, 2023).
glioma (3 papers, 2021 to 2025). A benign or malignant brain and spinal cord tumor that arises from glial cells (astrocytes, oligodendrocytes, ependymal cells). "In the LGG cohort from the TCGA dataset, ALDHs including ALDH2, ALDH6A1, ALDH5A1, ALDH9A1, ALDH1A1 were upregulated in WHO grade II gliomas while the increased expression of ALDH16A1, ALDH3B1, ALDH3A2, ALDH1A2, ALDH3A1 was found in WHO III grade gliomas." (PMID 35116021, 2021). "Based on our scoring system, three out of five ALDHs (ALDH3A1, ALDH3B1 and ALDH16A1) were identified as unfavorable biomarkers for gliomas." (PMID 35116021, 2021). "manifested that ALDH16A1 is considered a prognostic biomarker in gliomas." (PMID 36694633, 2023). "Accordingly, we focused on the role of ALDH3B1 and ALDH16A1 in gliomas." (PMID 35116021, 2021). "Importantly, silencing ALDH3B1 and ALDH16A1 expression induced cycle arrest at the G2/M phase and inhibited the epithelial-mesenchymal transition in the glioma cells." (PMID 35116021, 2021). "Critically, ALDH3B1 and ALDH16A1 could also affect the expression of cyclin B1 and aurora A, G2/M cell cycle checkpoints that modulate glioma cells proliferation." (PMID 35116021, 2021). "Therefore, ALDH3B1 and ALDH16A1 could promote glioma progression by regulating cell proliferation and migration." (PMID 35116021, 2021). "ALDH16A1 and COL3A1 play important roles in regulating the immunosuppressive microenvironment, tumor cell proliferation and EMT process in glioma." (PMID 40299526, 2025). "ALDH3B1 and ALDH16A1 are preferentially overexpressed in HGG and can promote the proliferation and migration of glioma cells by regulating cell cycle and EMT processes." (PMID 36694633, 2023). "Analysis of the TCGA dataset showed that ALDH16A1, ALDH3B1, ALDH1A3, ALDH3A1, ALDH7A1 were significantly increased in IDH wildtype gliomas, while ALDH2, ALDH6A1, ALDH5A1, ALDH1A1, ALDH1L2, ALDH18A1, ALDH1B1 expression were higher in IDH mutant gliomas than IDH wildtype gliomas." (PMID 35116021, 2021).
mast syndrome (2 papers, 2023 to 2025). "In Mast syndrome (SPG21), ALDH16A1 has been associated with masperdin, the protein in which causal mutations have been identified." (PMID 40898360, 2025).
diabetes (1 paper, 2012). "He discussed the structural determinants of ALDH16A1 during evolution and postulated that ALDH16A1 may interact with several other proteins associated with uric-acid formation, diabetes, vesicular transport and protein degradation." (PMID 23199258, 2012).
glioblastoma (1 paper, 2021). The most malignant astrocytic tumor (WHO grade IV). "Moreover, ALDH3B1 and ALDH16A1, two main contributors of the scoring system, could affect glioblastoma cell proliferation and migration by inducing cell-cycle arrest and the epithelial-mesenchymal transition." (PMID 35116021, 2021).
cancer (2 papers, 2023). A tumor composed of atypical neoplastic, often pleomorphic cells that invade other tissues. "ALDH16A1: The function of ALDH16A1 reported in cancer is limited." (PMID 36694633, 2023).
tumor (2 papers, 2021 to 2025). "Three out of the five components of our risk score, ALDH3A1, ALDH3B1 and ALDH16A1, were identified as tumor promoters." (PMID 35116021, 2021). "ALDH3B1 and ALDH16A1 could influence tumor cell proliferation and migration." (PMID 35116021, 2021). "Moreover, our in vitro experiments substantiated that ALDH3B1 and ALDH16A1 could affect tumor cells proliferation and epithelial-mesenchymal transition." (PMID 35116021, 2021).
ALDH16A1 also shares sentences with these, for which no sentence is quoted: hyperuricemia (1 paper); meningioma (1).